PRMT3 (protein arginine methyltransferase 3)
Diseases named in the same sentence as PRMT3 in open-access papers (continued):
Sharing a sentence is not in itself a finding about the gene and the disease.
Adenocarcinoma of the Lung (3 papers, 2023 to 2025). "In lung adenocarcinoma, the tumor suppressor DAL-1/4.1B interacts with PRMT3 and suppresses its methyltransferase activity, signifying a putative involvement of PRMT3 regulation in tumor progression." (PMID 37795435, 2023).
Hepatic steatosis (3 papers, 2022 to 2025). Steatosis is a term used to denote lipid accumulation within hepatocytes. "As such, pharmacological blockade of the PRMT3 function through treatment with the selective PRMT3 inhibitor SGC707 is able to overcome the LXR agonist-induced development of hepatic steatosis in C57BL/6 wild-type mice." (PMID 35013582, 2022). "Protein arginine methyltransferase 3 (PRMT3) has recently emerged from preclinical studies as a potentially interesting therapeutic target in the hepatic steatosis setting." (PMID 35013582, 2022). "Intriguingly, irisin reduced the expression of PRMT3 and ROS production as well as lipogenesis in PA-induced hepatic steatosis; however, the overexpression of PRMT3 reversed the antilipogenesis and anti-inflammatory function of irisin." (PMID 35035659, 2022). "Pharmacological inhibition of PRMT3 activity can thus theoretically serve as a therapeutic approach to battle both the development of hepatic steatosis and age-related cardiovascular and cognitive pathologies." (PMID 35013582, 2022). "Here we investigated whether pharmacological PRMT3 inhibition can diminish the hepatic steatosis extent and lower plasma lipid levels and atherosclerosis susceptibility." (PMID 35013582, 2022). "• By inhibiting PRMT3 activity, SGC707 reduces hepatic triglyceride accumulation and lowers plasma triglyceride levels, thereby ameliorating hepatic steatosis and dyslipidemia." (PMID 41583428, 2025).
lung carcinoma (3 papers, 2015 to 2026). "PRMT3 orchestrates metabolic reprogramming in non–small cell lung cancer through a TFAP2A-IDO1 pathway that stimulates kynurenine synthesis to promote radioresistance and immunosuppression, highlighting this axis as a putative therapeutic target." (PMID 41129671, 2026). "In conclusion, these findings delineate PRMT3-mediated Kyn metabolism as a mechanism of radioresistance and immune evasion in non–small cell lung cancer, offering valuable insights for potential interventions for treating patients with lung cancer." (PMID 41129671, 2026). "This is well reflected in the lung cancer data analyzed here wherein there is an upregulation of ALDH1A1; however, with a significant downregulation of RA-responsive genes, possibly owing to the elevated levels of PRMT3." (PMID 33495566, 2021). "In addition, it has been reported that PRMT3 and PRMT6 are mainly overexpressed in breast, bladder and lung cancer but not CRC." (PMID 26078354, 2015).
Miscarriage (3 papers, 2022 to 2025). A pregnancy that ends at a stage in which the fetus is incapable of surviving on its own, defined as the spontaneous loss of a fetus before the 22th week of pregnancy. "Recently, some studies have reported increased expression of PRMT1 and PRMT3, two type I enzymes, in the endometrium of LPS-induced endometritis rats and the decidua of recurrent miscarriage patients, respectively." (PMID 36195592, 2022). "In recurrent miscarriage (RM) models, macrophage PRMT3 downregulation reduces NO bioavailability, inducing trophoblast apoptosis and perturbing maternal-fetal interface function, suggesting PRMT3 involvement in pregnancy-related inflammation." (PMID 41583428, 2025). "Furthermore, animal experiments have also revealed that the PRMT3 inhibitor SGC707 could significantly reduce the embryo uptake rate in a mouse model prone to miscarriage, which demonstrates that the PRMT3/ADMA/NO pathway could be a potential target for the treatment of miscarriage." (PMID 37355665, 2023). "A recent study found that aDMA content and PRMT3 expression were increased in the decidua of recurrent miscarriage patients, primarily in macrophages but not in natural killer cells or stromal cells of the decidua." (PMID 36195592, 2022).
viral infection (3 papers, 2024 to 2025). "show that PRMT3 is upregulated in zebrafish in response to viral infection, and that overexpression of PRMT3 suppresses the cellular antiviral response." (PMID 39964832, 2025). "Mechanistic studies found PRMT3 expression increases 3.2-fold within 2 hours of viral infection, thereby suppressing virus-induced antiviral gene expression and interferon activation." (PMID 41583428, 2025). "Meanwhile, viral infection also induces cellular expression of metallothioneins, which chelate cytoplasmic Zn2+ to restrict excessive PRMT3 activation." (PMID 41583428, 2025). "Notably, the preferential modification of pattern recognition receptors by PRMT3 during viral infection is primarily driven by the coordinated regulation of substrate availability and the post-translational modification of PRMT3 itself." (PMID 41583428, 2025). "Moreover, a recent publication suggested that PRMT3 represses the innate immune response in viral infection by methylating cytosolic RNA and DNA sensors, such as RIG-I, MDA5, and cGAS50." (PMID 39256398, 2024).
acute leukemia (2 papers, 2024 to 2025). A clonal (malignant) hematopoietic disorder with an acute onset, affecting the bone marrow and the peripheral blood. "For ubiquitination, in acute leukemia PRMT3 degraders recruit E3 ubiquitin ligases to promote K48-linked ubiquitination and degradation of PRMT3." (PMID 41583428, 2025). "In this context, we described the discovery of a first‐in‐class PRMT3 selective degrader 11 by recruiting MDM2 E3 ubiquitin ligase that induced PRMT3 degradation in acute leukemia (AL) cells with a DC50 value of 2.5 μM." (PMID 39120042, 2024). "Importantly, 11 inhibited acute leukemia cell growth and is more effective than PRMT3 inhibitor SGC707." (PMID 39120042, 2024). "Importantly, 11 effectively inhibited the acute leukemia cell growth and is more effective than PRMT3 inhibitor SGC707, highlighting the advantages of PRMT3 degradation over inhibition." (PMID 39120042, 2024).
atherosclerosis (2 papers, 2022 to 2025). A disease characterized by the build-up of fatty material and calcium deposition in the arterial wall resulting in partial or complete occlusion of the arterial lumen. "• In non-alcoholic fatty liver disease and atherosclerosis, SGC707 inhibits PRMT3 activity, reduces hepatic triglyceride accumulation, affects white adipocyte size, alters plasma bile acid levels and TGR5 activation." (PMID 41583428, 2025). "However, while PRMT3 inhibitor SGC707 reduces serum lipids, it fails to alleviate atherosclerosis, indicating tissue-specific effects." (PMID 41583428, 2025).
chronic kidney disease (2 papers, 2024 to 2025). Impairment of the renal function secondary to chronic kidney damage persisting for three or more months. "The function of PRMT3 in chronic kidney disease (CKD) has also been a focus of interest." (PMID 39964832, 2025).
colon cancer (2 papers, 2020 to 2025). "PRMT3 has also been shown to be overexpressed in colon cancer tumors, possibly due to its role in regulating c-MYC polyubiquitination and stabilization." (PMID 40869229, 2025). "PRMT3 has also been correlated with a lower survival rate in patients with colon cancer compared to colon cancer patients with lower expression of PRMT3." (PMID 40869229, 2025).
glioma (2 papers, 2022 to 2025). A benign or malignant brain and spinal cord tumor that arises from glial cells (astrocytes, oligodendrocytes, ependymal cells). "Higher expression of PRMT3 is associated with poorer overall survival in glioma patients, and it has been confirmed that PRMT3 is crucial for the proliferation, survival, and tumour growth of GBM cells." (PMID 39964832, 2025). "The analysis of the CGGA glioma genome database revealed a positive correlation between expression of PRMT3 and HIF1A in both primary and recurrent gliomas." (PMID 36351894, 2022). "In the present study, we identify PRMT3 as the most significantly enriched PRMT enzyme family member in high- and low-grade gliomas, and show that the PRMT3 level is correlated with poorer prognosis in GBM patients." (PMID 36351894, 2022). "The expression level of PRMT3 was also higher in GBM (grade IV) than low-grade gliomas (grades II or III) in the TCGA database." (PMID 36351894, 2022). "Integrative GEPIA analysis of gliomas from TCGA (The Cancer Genome Atlas) and the human Genotype-Tissue Expression (GTEx) database, we found that PRMT3 was the most significantly enriched factor among all the PRMTs (based on fold change and p value) in both GBM and LGG." (PMID 36351894, 2022). "PRMT3 was mainly localized in the cytoplasm of the glioma cells." (PMID 36351894, 2022). "Higher PRMT3 expression predicted poorer overall survival rate in patients with gliomas." (PMID 36351894, 2022). "The study by Liao's team discovered that PRMT3 is among the most significantly enriched members of the PRMT family in both high‐grade and low‐grade gliomas." (PMID 39964832, 2025). "In this study, our functional analysis of gene expression networks revealed that among the PRMT family expression of PRMT3 was most significantly enriched in both GBM and low-grade gliomas." (PMID 36351894, 2022). "In this study, we explored the expression levels and prognostic values of PRMT genes in gliomas using Gene Expression Profiling Interactive Analysis (GEPIA) and found that PRMT3 is the most significantly enriched member of the PRMT family in high- and low-grade gliomas." (PMID 36351894, 2022).
renal fibrosis (2 papers, 2022 to 2025). A final common manifestation of a wide variety of chronic kidney diseases characterized by glomerulosclerosis and tubulointerstitial fibrosis. "We aimed to study the role of PRMT3 in renal fibrosis and explored its underlying mechanisms." (PMID 36177327, 2022). "Animal models and clinical evidence further validate the role of the PRMT3-ADMA axis in renal fibrosis." (PMID 41583428, 2025). "Exogenous injection of ADMA reversed the aggravated fibrotic phenotype in PRMT3-knockout mice, directly confirming that ADMA acts as a downstream effector molecule of PRMT3 in suppressing renal fibrosis." (PMID 41583428, 2025). "To find out which family member of type I PRMTs is renal protective, we initiated the current study to investigate the role of PRMT3 in renal fibrosis." (PMID 36177327, 2022). "The role of PRMT3 in renal fibrosis was studied in vivo in the UUO mouse model using Prmt3 gene knockout mice." (PMID 36177327, 2022). "In the UUO mouse model, we found that homozygous deletion of Prmt3 gene promoted renal fibrosis as shown by Masson staining and Western blotting analysis." (PMID 36177327, 2022). "Furthermore, delivery of exogeneous ADMA into UUO kidneys with Prmt3 deletion attenuated renal fibrosis in Prmt3 knockout UUO kidneys." (PMID 36177327, 2022). "Thus, we conclude that PRMT3 is protective against renal fibrosis." (PMID 36177327, 2022). "Besides the general product of ADMA, PRMT3 may inhibit renal fibrosis through modification of certain transcriptional factors or enzymes." (PMID 36177327, 2022). "However, the role of PRMT3 in renal fibrosis is currently unknown." (PMID 36177327, 2022).
adenoma (1 paper, 2013). A neoplasm arising from the epithelium. "Quantitative analysis of microarray data confirmed that these methyltransferases, which included Setd3, Setd5, Suv39h2, Smyd3, Prmt3, Prmt6, Nsd1, and Nsd2 were up-regulated in metastases compared to adenomas, carcinomas, or disseminated cells." (PMID 23520493, 2013).
clear cell renal carcinoma (1 paper, 2024). A malignant epithelial neoplasm of the kidney characterized by the presence of lipid-containing clear cells within a vascular network. "We also found a negative correlation between PRMT3 expression and CD8+ T cell infiltration in immunotherapy-sensitive cancer types such as skin cutaneous melanoma (SKCM) and clear cell renal carcinoma (KIRC)." (PMID 39256398, 2024).
Cognitive impairment (1 paper, 2025). Abnormal cognition is characterized by deficits in thinking, reasoning, or remembering. "Together, these findings demonstrate that neuronal overexpression of PRMT3 in the EC region aggravates tau hyperphosphorylation and exacerbates cognitive deficits in PS19 tauopathy mice." (PMID 40344412, 2025). "In vitro and in vivo study highlighted the therapeutic efficacy of SGC707, a potent allosteric inhibitor of PRMT3, in reducing tau hyperphosphorylation and reversing cognitive deficits." (PMID 40344412, 2025).
colon adenocarcinoma (1 paper, 2025). "Moreover, PRMT3 is significantly upregulated in CRC tumors (colon adenocarcinoma, COAD; rectum adenocarcinoma, READ) compared with normal control." (PMID 39868792, 2025).
colorectal tumor (1 paper, 2021). "The findings showed that PRMT3 expression level in colorectal tumor tissue was significantly higher compared with that of normal colorectal tissues." (PMID 34753906, 2021). "Results showed that PRMT3 was significantly upregulated in colorectal tumor tissues compared with the expression level in adjacent normal tissues." (PMID 34753906, 2021). "Moreover, PRMT3 expression level of colorectal tumor tissues was positively correlated with HIF1α expression level of colorectal tumor tissues." (PMID 34753906, 2021).
endometriosis (1 paper, 2022). The growth of functional endometrial tissue in anatomic sites outside the uterine body. "Our qPCR showed that the expression level of PRMT5, but not PRMT1 or PRMT3, was obviously decreased in the eutopic endometrium of endometriosis patients compared with that in fertile controls." (PMID 36195592, 2022).
epilepsy (1 paper, 2024). A brain disorder characterized by episodes of abnormally increased neuronal discharge resulting in transient episodes of sensory or motor neurological dysfunction, or psychic dysfunction. "Nav2, Ptpn5, Ldha, and Dbx1 are deemed higher priority as they have a direct biological association with seizures or epilepsy, while Prmt3 and Slc6a5 have an indirect association." (PMID 38862622, 2024).
esophageal squamous cell carcinoma (1 paper, 2025). Esophageal squamous cell carcinoma (ESCC) is a type of esophageal carcinoma (EC) that can affect any part of the esophagus, but is usually located in the upper or middle third. "Our study identifies a novel mechanism of LDHA post‐translational activation through methylation at R106 by AHCY‐recruited PRMT3, revealing a previously unknown layer of glycolytic regulation that promotes esophageal squamous cell carcinoma progression." (PMID 41163796, 2025). "Moreover, our study delineates a novel pathway in esophageal squamous cell carcinoma whereby STIP1 enhances the interaction between AHCY and LDHA, enabling AHCY to recruit PRMT3 to methylate LDHA at R106." (PMID 41163796, 2025).
hepatitis B virus infection (1 paper, 2022). A viral infection caused by the hepatitis B virus. "PRMT3 upregulation was significantly correlated with hepatitis B virus infection, increased tumour number, larger tumour size and higher tumour‐nodule‐metastasis stage." (PMID 35090076, 2022).
lentivirus infection (1 paper, 2022). Virus diseases caused by the Lentivirus genus. "As the expression of PRMT3 was relatively higher in SNU398 cells and its expression in Huh7 cells relatively low, we selected these two HCC cell lines to establish stable cell lines SNU398‐Lv‐shPRMT3‐1, SNU398‐Lv‐shPRMT3‐2 and Huh7‐Lv‐PRMT3 using lentivirus infection." (PMID 35090076, 2022).
malignant glioma (1 paper, 2022). A grade III or grade IV glioma arising from the central nervous system. "In conclusion, we demonstrated that PRMT3, highly enriched in malignant gliomas, is essential for GBM growth in vitro and in vivo at least in part by activating HIF1α and glycolysis signaling." (PMID 36351894, 2022). "Thus, our study demonstrates that PRMT3 promotes GBM progression by enhancing HIF1A-mediated glycolysis and metabolic rewiring, presenting a point of metabolic vulnerability for therapeutic targeting in malignant gliomas." (PMID 36351894, 2022).
melanoma (1 paper, 2025). A malignant, usually aggressive tumor composed of atypical, neoplastic melanocytes. "Next, we analyzed patient cohorts with clinical data (GSE91061 for melanoma and ERP117672 for HCC) and found that PRMT3 expression is significantly higher in the anti-PD-1 response group compared to the non-response group." (PMID 40050608, 2025). "Furthermore, we analyzed public patient cohorts (GSE91061 for melanoma, ERP117672 for HCC) on anti-PD-1 treatment and found that PRMT3 expression is significantly higher in responders compared to non-responders." (PMID 40050608, 2025).
Nephropathy (1 paper, 2022). A nonspecific term referring to disease or damage of the kidneys. "The renal protective effect of PRMT3 was further confirmed in FA induced nephropathy by demonstrating that heterozygous deletion of Prmt3 increased BUN levels, collagen deposition and fibrotic marker expression." (PMID 36177327, 2022).
neuroblastoma (1 paper, 2025). Neuroblastoma (NB) is the most common solid, extracranial childhood tumor. "To explore the effects of PRMT3 on tau phosphorylation, we knocked down PRMT3 in mouse neuroblastoma cell line, Neuro2a." (PMID 40344412, 2025).
Osteopenia (1 paper, 2019). Osteopenia is a term to define bone density that is not normal but also not as low as osteoporosis. "Moreover, administration of Prmt3 shRNA or a chemical inhibitor of PRMT3 (SGC707) caused an osteopenia phenotype in mice." (PMID 31378783, 2019).
osteoporosis (1 paper, 2019). A condition of reduced bone mass, with decreased cortical thickness and a decrease in the number and size of the trabeculae of cancellous bone (but normal chemical composition), resulting in increased fracture incidence. "Moreover, PRMT3 expression level was increased during MSCs osteoblastic differentiation and decreased in BMMSCs from OVX mice, suggesting that PRMT3 plays a critical role in MSC-mediated osteogenesis and therefore the pathogenesis of osteoporosis." (PMID 31378783, 2019).
Pruritus (1 paper, 2022). Pruritus is an itch or a sensation that makes a person want to scratch. "However, more insight into the in vivo pharmacology of SGC707 and tissue-specific physiological roles of PRMT3 is needed to potentially be able to overcome the unwanted hepatic cholesterol and plasma bile acid accumulation and development of pruritus upon PRMT3 inhibition." (PMID 35013582, 2022). "Since PRMT3 gene expression levels were too low to be reliably detected in all skin samples (Ct > 35), it is anticipated that the pruritus induction was not due to an effect of SGC707 locally within the skin." (PMID 35013582, 2022).